ZNF683 (zinc finger protein 683)
Diseases named in the same sentence as ZNF683 in open-access papers (continued):
Sharing a sentence is not in itself a finding about the gene and the disease.
tumor (continued). "Next, we detected numerous lymphocyte development and function associated pathways that are significantly associated with ZNF683 (HOBIT), STAT2, and IRF3 expression, indicating that these TFs may regulate the priming, and their downstream functionalities of tumour-infiltrating NK and CD8+ T cells." (PMID 39877370, 2024). "For both subsets of γδ TRM, ZNF683 (Hobit), CD81, CD82, and IFNG expression is higher in the tumor compared to normal tissue." (PMID 39454432, 2024). "Upon antigen stimulation, it is possible that ADGRG1, as a member of the ZNF683 regulatory network, participates in the modulation of T cell effector function and NK transition, mediating the unique phenotype of AML tumor-reactive T cells." (PMID 39243082, 2024). "In HNSCC, CD8+ T cells that underwent clonal expansion during ICB treatment expressed elevated tissue-resident memory (CD103+ZNF683+) and cytotoxicity programs (GZMB+PD-1+CTLA-4+) and show tumor-specific recognition." (PMID 37881432, 2023). "Focusing on ICI-responsive GCs, we found a substantial proportion of pre-treatment ISG-15+CD8+ T clonotypes in effector T-cell populations (CXCL13+CD8+ T, ZNF683+ Tem and GZMK+ Tem) of post-treatment EBV (+) tumours." (PMID 37735150, 2023). "CD8-C1 highly expressed ZNF683 and ITGAE, represented a subpopulation of tissue-resident memory T cells (TRMs), which was reported as a considerable origin of tumor neoantigen specific T cells." (PMID 36138435, 2022). "ZNF683+ Trm cells revealed higher expression of cytotoxic cytokines and immune checkpoint molecules and activated TCR signalling, which suggests that ZNF683 + Trm plays an antitumor role within the tumour." (PMID 36869093, 2023). "NK cells transfected with ZNF683 showed decreased expression of cytolytic molecules, high levels of exhaustion‐related markers, and failed to exert efficient cytotoxicity against tumour cells." (PMID 36245253, 2022). "To explore the intercellular interactions between tumor and T cells within TME, we applied Ro/e scoring to identify T cell subclusters enriched in the tumor tissues, specifically focusing on CD4_Exhausted, CD8_Teff, CD8_Tc17, Treg_Suppressive, Cycling T cells, CD8_GZMK_ZNF683 and CD8_Exhausted." (PMID 40452847, 2025).
cancer (13 papers, 2015 to 2025). A tumor composed of atypical neoplastic, often pleomorphic cells that invade other tissues. "Of note, although ZNF683 was previously associated with a positive response to therapy in specific cancer types, exploring its expression in multiple datasets clearly shows its upregulation in non-responding patients." (PMID 40187353, 2025). "Recent research has identified zinc finger protein 683 (ZNF683) expression as a candidate marker of cancer‐specific TRM cells in CRC." (PMID 39802636, 2025). "Our findings provide new insights into the use of Trm cells as a predictive factor of CRC prognosis, ZNF683 as a candidate marker for cancer-specific Trm, and the characteristics of ZNF683+ Trm." (PMID 36869093, 2023). "These consistent findings lead to a confirmation of ZNF683+ NK cell present in cancer context and highlight potential roles of ZNF683 in regulating NK cell function." (PMID 37259170, 2023). "We identified ZNF683 as one of the makers of cancer-specific Trm cells, which appear to have high cytotoxicity, by comparing Trm cells under various conditions at the single-cell level." (PMID 36869093, 2023). "In addition, we identified the ZNF683 expression as one of the candidate markers of cancer-specific Trm cells." (PMID 36869093, 2023). "TBX21 has been reported to be upregulated by stimuli such as TCR signalling and IFN-γ signalling, thereby supporting the hypothesis that ZNF683+ Trm cells are cancer-specific Trm cells." (PMID 36869093, 2023). "ZNF683 was more upregulated in high-infiltrating Trm cells in cancer, which may be related to cancer-specific Trm than low-infiltrating Trm in cancer." (PMID 36869093, 2023). "We determined the characteristics of ZNF683+ Trm cells by comparing ZNF683+ and ZNF683– Trm cells because ZNF683 was hypothesised as a cancer-specific marker." (PMID 36869093, 2023). "inferred two paths of T cell exhaustion via pan-cancer analysis: the first path (P1) through GZMK+ effector memory T (Tem) cells and the second path (P2) through ZNF683+CXCR6+ tissue-resident memory T (Trm) cells." (PMID 39393173, 2024). "ZNF683+ Trm cells, identified as cancer-specific Trm cells in this study, have higher IFNG and GZMB expression compared with ZNF683– Trm cells, suggesting that cancer-specific Trm cells have high cytotoxic potential." (PMID 36869093, 2023). "Additionally, IC50 of the mentioned anti-cancer drugs, especially Nelarabine, is highly positively correlated with the expressions of CD2, ZNF683 and KLRB1, which means drug resistance." (PMID 36090993, 2022). "For example, ZNF273 was correlated with four motifs in CRC and ZNF683 was correlated with nine motifs in KIRC; neither of these TFs has ever been associated with cancer." (PMID 25994056, 2015).
infection (2 papers, 2022 to 2024). The state of being infected such as from the introduction of a foreign agent such as serum, vaccine, antigenic substance or organism. "The results of an in vitro infection experiment showed that after knockdown of ZNF683 in human PBMCs, HIV replication increased significantly, as indicated by an increased viral load." (PMID 35458449, 2022). "In future research, we will perform more animal experiments and collect samples at different time points after infection to verify the function of ZNF683 in HIV infection." (PMID 35458449, 2022). "Research have given that high expression of ZNF683 facilitate the proliferation and excretion of IFN-γ by CD8+T cells following infection." (PMID 39872521, 2024). "Due to the important role of ZNF683 in the immune system, we speculate that high expression of ZNF683 promotes CD8+ T cell IFNγ secretion and proliferation after infection to inhibit viral replication and slow the disease progression." (PMID 35458449, 2022). "Higher expression of ZNF683 promotes CD8+ T cell IFNγ secretion and proliferation after infection." (PMID 35458449, 2022).
ZNF683 also shares sentences with these, for which no sentence is quoted: colitis (1 paper); head and neck squamous cell carcinoma (1); ischemic stroke (1); mastitis (1); psoriasis (1); renal cell carcinoma (1); Sepsis (1).